SLC6A19 (solute carrier family 6 member 19)
Description:
Transporter that mediates resorption of neutral amino acids across the apical membrane of renal and intestinal epithelial cells. This uptake is sodium-dependent and chloride-independent. Requires CLTRN in kidney or ACE2 in intestine for cell surface expression and amino acid transporter activity.
Synonyms: B0AT1; HND
Tractability: Small molecule: a structure with a bound ligand is known; it belongs to a druggable protein family. Antibody: UniProt places it where antibodies can reach, with high confidence; its Gene Ontology location is reachable by antibodies, with high confidence; UniProt predicts a signal peptide or a membrane-spanning region.
Gene: Protein-coding gene on chromosome 5 (1,201,595 to 1,225,111, forward strand). Ensembl gene ENSG00000174358.
Subcellular location: Cell membrane; Apical cell membrane
Pathways (Reactome):
Disease: Defective transport of amino acids by SLC6A19 causes Hartnup disorder (HND); Defective transport of neurotransmitters by SLC6A19 causes Hartnup disorder (HND)
Transport of small molecules: Amino acid transport across the plasma membrane; SLC-mediated transport of neurotransmitters
Gene Ontology:
Molecular function: alanine:sodium symporter activity; glycine:sodium symporter activity; neutral L-amino acid transmembrane transporter activity; protein binding; amino acid transmembrane transporter activity; transmembrane transporter activity
Biological process: amino acid import across plasma membrane; amino acid transport; neurotransmitter transport; neutral amino acid transport; sodium ion transmembrane transport; viral life cycle; alanine transport; glycine transport; response to nutrient
Cellular component: apical plasma membrane; brush border membrane; extracellular exosome; plasma membrane; transmembrane transporter complex; membrane
Genetic constraint (gnomAD): Loss-of-function variants: 69 observed, 70.21 expected, observed/expected ratio (o/e) 0.98, 90% interval 0.81 to 1.2. The upper end of that interval is the gene's LOEUF score, 1.2, which puts it in group 5 of 6, group 1 being the genes least tolerant of losing a copy. Missense variants: 813 observed, 878.65 expected, observed/expected ratio (o/e) 0.93, 90% interval 0.87 to 0.98. Synonymous variants: 392 observed, 386.73 expected, observed/expected ratio (o/e) 1.01, 90% interval 0.93 to 1.1.
Gene-disease validity (ClinGen):
ClinGen rates the evidence that SLC6A19 causes each of these diseases.
Hartnup disease (autosomal recessive): Definitive.
Homologues: Orthologues: macaque SLC6A19 (92% identical), rat Slc6a19 (87% identical), mouse Slc6a19 (87% identical), pig SLC6A19 (86% identical), dog SLC6A19 (86% identical), guinea pig SLC6A19 (83% identical), tropical clawed frog slc6a19 (75% identical), zebrafish slc6a19a.2 (68% identical), zebrafish slc6a19b (68% identical), zebrafish slc6a19a.1 (68% identical), chimpanzee SLC6A19 (57% identical). Paralogues in human: SLC6A18 (51% identical), SLC6A20 (44% identical), SLC6A15 (42% identical), SLC6A17 (41% identical), SLC6A5 (35% identical), SLC6A12 (35% identical), SLC6A9 (33% identical), SLC6A13 (33% identical), SLC6A8 (33% identical), SLC6A3 (33% identical), SLC6A2 (33% identical), and 6 more.
Diseases named in the same sentence as SLC6A19 in open-access papers:
SLC6A19 is named in the same sentence as 44 diseases in open-access papers, as found by Europe PMC text mining. Sharing a sentence is not in itself a finding about the gene and the disease. The quoted sentences say what the papers report.
Hartnup disease (22 papers, 2015 to 2026). "Mutations in SLC6A19 are implicated in Hartnup disease, a metabolic disorder characterized by defective amino acid transport." (PMID 40852587, 2025). "In humans, loss-of-function mutations in SLC6A19 cause Hartnup disorder, a generally benign condition characterized by increased urinary excretion of Phe as well as other neutral amino acids, also referred to as Hartnup amino acids." (PMID 39513367, 2024). "Loss-of-function mutations in SLC6A19, the “transporter proper”, cause Hartnup disease, an inborn error of amino acid transport." (PMID 35204736, 2022). "In Hartnup disorder, SLC6A19 deficiency induces a decrease in intestinal absorption and renal reabsorption of tryptophan, leading to an elimination of tryptophan and derivatives in feces and urine." (PMID 36188218, 2022). "Autosomal recessive inheritance of SLC6A19 mutations in humans leads to poor absorption of AAs from the gut, or poor retention of AAs by the kidneys, causing Hartnup disorder." (PMID 36611813, 2022). "This is, however, due to the fact that SLC9A3 is also a cystic fibrosis modifier gene, SLC4A1 is also associated with spherocytosis, and SLC6A19 also causes Hartnup disease, all of which are comparatively frequent conditions." (PMID 35456490, 2022). "This is in agreement with findings from patients with Hartnup disease, where bi-allelic loss-of-function mutations in SLC6A19 lead to a reabsorption defect of histidine in renal tubular cells." (PMID 33574263, 2021). "In contrast, the expression of deleterious variants of SLC6A19 showed impaired leucine uptake, providing evidence that reduced amino acid transport through SLC6A19 is indeed the causative factor in Hartnup disease." (PMID 34041853, 2021). "The epithelial neutral amino acid transporter B0AT1 (SLC6A19) was initially identified as the molecule mutated in the rare condition Hartnup disorder." (PMID 32180718, 2020). "Mutations in SLC6A19 are found in Hartnup disorder patients, which is diagnosed by the spillover of neutral amino acids in the urine." (PMID 30441827, 2018). "Inactivating mutations in B0AT1 (SLC6A19) in humans are known to cause Hartnup disorder, a largely benign disorder, which is characterised by large amounts of neutral amino acids spilling over into the urine." (PMID 25973388, 2015). "Mutations in the SLC6A19 gene cause to malfunctioning of this transporter, leading to Hartnup disorder, an autosomal recessive condition characterized by urinary loss of neutral amino acids due to an inability to transport them across the cellular brush border." (PMID 40852587, 2025). "JNT-517 caused a dose-dependent increase in urinary Hartnup amino acids in both SAD and MAD cohorts, reproducing the aminoaciduria signature observed in Hartnup disorder resulting from loss-of-function mutations in SLC6A19 and corroborating the pharmacology of SLC6A19 inhibition in mice." (PMID 39513367, 2024). "Previous studies have shown that genetic loss of Slc6a19 in mice recapitulates the phenotype observed in Hartnup disorder, characterized by increased urinary excretion of amino acids, including Phe, without causing a pathological decrease in plasma amino acid levels." (PMID 39513367, 2024). "Hartnup disease is caused by a deficiency of the sodium-dependent neutral amino acid transporter in the proximal kidney tubules and jejunum, resulting from a mutation in the solute carrier family 6 member 19 (SLC6A19) gene." (PMID 37759536, 2023). "Mutations in SLC6A19 cause Hartnup disease which is characterized by neutral aminoaciduria." (PMID 39086962, 2022). "Indeed, inactivating mutations of SLC6A19 cause the Hartnup disorder, which is mainly characterized by a tryptophan deficiency." (PMID 36188218, 2022). "Additionally, human subjects bearing an SLC6A19 loss-of-function mutation develop a disorder called Hartnup disease, characterized notably by the co-occurrence of neuropsychiatric symptoms and low blood levels of neutral amino acids." (PMID 34638785, 2021).
Hartnup disease (continued). "Indeed, homozygous or compound heterozygous mutations in the neutral amino acid transporter SLC6A19, which is required for tryptophan transport, cause a pellagra‐like disorder known as Hartnup disease, a syndrome with similar symptoms to niacin deficiency." (PMID 34041853, 2021). "In addition, pathways associated with inborn errors of metabolism—such as Hartnup disorder (defective SLC6A19), 3‐phosphoglycerate dehydrogenase deficiency, and non‐ketotic hyperglycinemia—were upregulated, indicating restoration of disrupted metabolic processes." (PMID 41355579, 2026). "Hartnup disease (OMIM #234500) is a rare, autosomal recessive disorder caused by pathogenic variants in the SLC6A19 gene (5p15.33), encoding the sodium-dependent neutral amino acid transporter B0AT1." (PMID 41464651, 2025). "This pharmacological effect mimics the loss of function phenotype observed in SLC6A19 knockout mice and humans with hartnup disorder, who exhibit aminoaciduria due to the defective SLC6A19 gene." (PMID 41142409, 2025). "An intriguing and interesting observation was made when SLC6A19-null mice were studied as a model for Hartnup disease." (PMID 35204736, 2022). "Mice in which Slc6a19 has been knocked out (Slc6a19−/−) exhibit symptoms of neutral aminoaciduria characteristic of Hartnup disorder." (PMID 36611813, 2022). "Patient 6, a young female with a history of androgenetic alopecia presenting with pellagra-like dermatitis secondary to sun exposure, was diagnosed with Hartnup disease (MIM: 234500), caused by compound heterozygous variants in SLC6A19 (p.Asp173Asn, p.Glu519Gly)." (PMID 35606766, 2022). "The absence of SLC6A19 in the kidney is characterized by the loss of amino acids in urine, a hallmark of Hartnup disorder." (PMID 30441827, 2018).
COVID-19 (5 papers, 2021 to 2022). A disease caused by infection with severe acute respiratory syndrome coronavirus 2. "The genetic variant associations in RORA, SLC12A6, and SLC6A19 genes were observed in genome-wide association study (GWAS) of COVID-19 susceptibility." (PMID 34512723, 2021). "This binding can decrease ACE2 receptor expression, resulting in dysregulation of B0AT1 (broad neutral amino acid transporter, SLC6A19), which influences, COVID-19-associated diarrhea." (PMID 34760721, 2021). "SLC6A19 SNPs were associated with severe COVID-19 phenotype definitions, i.e., COVID-19 with very severe respiratory confirmed (rs76067074, p = 2.65e-3) and hospitalized COVID-19 (rs76067074, p = 2.52e-4)." (PMID 34512723, 2021). "Three genes—RORA, SLC12A6, and SLC6A19—showed associations with multiple COVID-19 phenotypes." (PMID 34512723, 2021). "A low expression of Solute Carrier Family 6 Member 19 (SLC6A19) has been observed on the surface of the small intestine cells of COVID-19 patients because of its co-internalization along the ACE2, the preferred receptor for SARS-CoV-2." (PMID 36293182, 2022). "Hints for the role of Slc6a19 in COVID-19 come from population genetic studies." (PMID 33757938, 2021). "The main urine amino acids during COVID-19 include neutral amino acids (e.g., phenylalanine, leucine, tryptophan) and imino acids (e.g., proline), which are transported by B0AT1/SLC6A19 and SIT1/SLC6A20, respectively." (PMID 35705608, 2022).
Aminoaciduria (3 papers, 2024 to 2025). An increased concentration of an amino acid in the urine. "Treatment of Pahenu2 mice with a SLC6A19 inhibitor caused widespread aminoaciduria, including increases in urinary Phe, as well as a dose-dependent reduction in plasma Phe." (PMID 39513367, 2024). "Inhibition of SLC6A19 causes aminoaciduria and lowers plasma Phe in a PKU mouse model." (PMID 39513367, 2024). "Mutations in SLC6A19 have been associated with aminoaciduria." (PMID 38287030, 2024). "The review highlighted 9 genes associated with aminoacidurias, including SLC3A1 (rBAT), SLC7A9 (bo,+AT), SLC6A19 (BoAT1), SLC7A7 (y+LAT1), SLC7A6 (y+LAT2), SLC36A2 (PAT-2), SLC6A20 (SIT-1), SLC6A18 (BoAT3), and SLC1A1 (EAAT3)." (PMID 41142409, 2025).
Obesity (3 papers, 2018 to 2022). Accumulation of substantial excess body fat. "The association of SLC6A19 deficiency to protection against obesity has thus far been demonstrated only in mice." (PMID 35204736, 2022). "The well-established biological functions of FGF21 as a key regulator of energy balance, glucose homeostasis, fat metabolism and insulin sensitivity provide clues as to the SLC6A19 loss-associated protection against obesity and metabolic syndrome." (PMID 35204736, 2022). "The mEC1 population showed an obesity-induced downregulation of transporters of major ions (Slc34a1, Slc4a4, Slc22a8, Slc13a1, Slc22a18 and Slc5a12), neutral amino acids (Slc6a19) and glucose (Slc5a2)." (PMID 36400935, 2022). "In the present review, we highlight the unusual involvement of selective amino acid transporters in macropinocytosis (SLC38A5/SLC38A3) and diet-induced obesity/metabolic syndrome (SLC6A19/SLC6A14/SLC6A6)." (PMID 35204736, 2022). "These novel findings suggest that SLC6A19 could potentially be exploited as a useful therapeutic target for obesity, type 2 diabetes and metabolic syndrome." (PMID 35204736, 2022). "In the context of the possible involvement of GPR142 in protecting against obesity/metabolic syndrome seen in SLC6A19-null mice, it is important to highlight that tryptophan and phenylalanine, the amino acid agonists for the receptor, are among the preferred substrates for SLC6A19." (PMID 35204736, 2022). "The rationale is as follows: if the deletion of SLC6A19 protects against obesity/metabolic syndrome and improves glycemic control, a similar metabolic outcome could be achieved with pharmacological inhibition of the transporter." (PMID 35204736, 2022). "Therefore, it is not known at present whether SLC6A19 deficiency would protect against obesity and obesity-associated clinical sequelae in humans." (PMID 35204736, 2022). "The recent discovery of the role of SLC38A5 in promoting macropinocytosis and the contrasting roles of SLC6A19 and SLC6A14 in diet-induced obesity and metabolic syndrome highlights these novel and unconventional functions of specific amino acid transporters." (PMID 35204736, 2022). "Mice lacking SLC6A19 show signs of protein restriction, have improved glucose tolerance, and are protected from diet-induced obesity." (PMID 30441827, 2018).
pellagra (3 papers, 2015 to 2023). "There is also a rare genetic form of pellagra, Hartnup disease, caused by autosomal recessive mutations in SLC6A19 that also results in niacin deficiency because of impaired absorption and retention of neutral amino acids, including the niacin precursor tryptophan." (PMID 37503611, 2023). "This disease is caused by a mutation in solute carrier family 6 member 19 (SLC6A19; the ‘genocopy’) but a very similar clinical manifestation occurs in cases of dietary niacin deficiency, a condition known as pellagra (the ‘phenocopy’)." (PMID 25628760, 2015).
colorectal cancer (2 papers, 2019 to 2025). A primary or metastatic malignant neoplasm that affects the colon or rectum. "To explore what SLC6A19 might be doing in colorectal cancer, we first looked at its expression at single-cell resolution." (PMID 40990012, 2025).
diabetes (2 papers, 2021 to 2022). "A recent review reported that the expression of amino acid transporter Slc6a19, which has a higher affinity to neutral amino acids than branched-chain amino acids, was increased in animal models of diabetes." (PMID 34686904, 2022). "The research focus on SLC6A19 as a potential therapeutic target in diabetes should be for type 2 diabetes for now, with the possibility of reconsidering it as a target for type 1 diabetes as we learn more." (PMID 34677380, 2021). "Diabetes incidence by 30 weeks of age was 59.5% (22/37) and 69.0% (20/29) in NOD.Slc6a19+/+ and NOD.Slc6a19−/− mice, respectively (hazard ratio 0.77, 95% confidence interval 0.41–1.42; Mantel-Cox log rank test: p = 0.37)." (PMID 34677380, 2021). "The median survival time without diabetes was 28 and 25 weeks for NOD.Slc6a19+/+ and NOD.Slc6a19−/− mice, respectively (ratio 1.1, 95% confidence interval 0.6–2.0)." (PMID 34677380, 2021). "Diabetes developed as early as 14 weeks of age in two NOD.Slc6a19−/−, however, the median survival time without diabetes was 28 and 25 weeks for NOD.Slc6a19+/+ and NOD.Slc6a19−/− mice, respectively (ratio 1.1, 95% confidence interval 0.6–2.0)." (PMID 34677380, 2021).
dyslipidemia (2 papers, 2021 to 2022). "F0AT1 (SLC6A19) inhibitor ameliorates the lipotoxicity and dyslipidemia to induce endogenous fibroblast growth factor 21 (FGF21) to treat fatty liver associated diseases." (PMID 34884968, 2021).
Hyperglycinuria (2 papers, 2022). An increased concentration of glycine in the urine. "In the present study, we report a rare case of hyperglycinuria combined with nephrolithiasis in which a mutation in the SLC6A19 gene was detected by genetic analysis." (PMID 36434624, 2022). "Therefore, the patient was diagnosed with hyperglycinuria based on the typical symptoms (nephrolithiasis), laboratory testing (high urine glycine and oxalate levels), stone biochemical composition analysis (calcium oxalate), and relevant gene mutation (SLC6A19)." (PMID 36434624, 2022). "The SLC6A19 gene may have been significant in the development of hyperglycinuria in a Chinese young man." (PMID 36434624, 2022).
Hypertension (2 papers, 2016 to 2017). The presence of chronic increased pressure in the systemic arterial system. "Defects in three of these genes, Slc6a19, Slc4a4, and Lrp2 have been linked to hypertension." (PMID 27462279, 2016). "Except defect in Slc6a19 (encodes an amino acid transporter B°AT1) has been linked to hypertension, most genes are not relevant to hypertension and kidney disease." (PMID 28368364, 2017).
iminoglycinuria (2 papers, 2022). A metabolic disorder resulting from defective renal tube reabsorption of proline, hydroxyproline and glycine. "Moreover, SLC4A1 and SLC6A19 are part of the panel because they are associated with distal renal tubular acidosis (Orphacode 93608), and iminoglycinuria (Orphacode 42062), respectively, two co-morbidities of nephrolithiasis." (PMID 35456490, 2022).
nephrolithiasis (2 papers, 2022). The presence of a calculus in the pelvis of the kidney; this is most often composed of mineral salts and proteins. "For example, for nephrolithiasis (PanelApp panel 149), SLC9A3, SLC4A1, and SLC6A19 appear on the top of the gene list." (PMID 35456490, 2022).
type 2 diabetes (2 papers, 2021 to 2022). "This suggests amino acid off-loading through Slc6a19 deficiency reduces islet beta cell work, and consequently has the potential to reduce islet beta cell metabolic stress for prevention of both type 1 and type 2 diabetes." (PMID 34677380, 2021). "Thus, it remains possible that SLC6A19 could become a therapeutic target for certain subgroups at high risk of type 1 diabetes, such as those who are overweight or have overlapping genetic risk for type 1 and type 2 diabetes." (PMID 34677380, 2021).
viral infection (2 papers, 2022 to 2024). "Consistently, the transcriptional levels of Ace2 and Slc6a19, two key genes involved in tryptophan uptake, were significantly decreased in both mouse and human organoids after viral infection." (PMID 38562420, 2024). "Conversely, Tlr3 or Stat1 deletion and Nuclear factor kappa B inhibition prevented the responses to viral infection and restored the levels of Ace2 and Slc6a19." (PMID 38562420, 2024). "Notably, a heterodimer of ACE2 and either SLC6A19 or SLC6A20 serves as a binding site for the SARS-CoV-2 spike protein, which may facilitate viral infection." (PMID 35910207, 2022).
autism spectrum disorder (1 paper, 2022). A spectrum of developmental disorders that includes autism, and Asperger syndrome. "Moreover, the research found that in Chd8+/− mice model of autism spectrum disorder (ASD), increased expression of neutral amino acid transporters Slc6a19, Slc7a8, and Slc7a15 resulted in increased serum glutamine and tryptophan levels." (PMID 36620044, 2022).
celiac disease (1 paper, 2024). An autoimmune genetic disorder with an unknown pattern of inheritance that primarily affects the digestive tract. "However, the only common DMR associated gene between CVID_N, CVID_IEL and celiac disease compared to controls, was SLC6A19 (location in chr5 between position 1,203,001 and 1,204,000, mean methylation difference 28.9%, 1408 base pairs away from the transcription start site)." (PMID 38780872, 2024).